CXCL8 (C-X-C motif chemokine ligand 8)
Diseases named in the same sentence as CXCL8 in open-access papers (continued):
Sharing a sentence is not in itself a finding about the gene and the disease.
tuberculosis (50 papers, 2005 to 2026). A chronic, recurrent infection caused by the bacterium Mycobacterium tuberculosis. "Notably, persistent CXCL8 overexpression in peripheral blood of infected cattle forms a stable diagnostic signature, validated as a biomarker suite for tuberculosis surveillance." (PMID 40642274, 2025). "Previously, increasing levels of CXCL8 have been shown to be associated with fatal tuberculosis." (PMID 20041183, 2009). "Cytokines such as chemokine IL-8 (CXCL-8) are often detected in patients with tuberculosis, and their role in active tuberculosis has been paid more and more attention." (PMID 36248872, 2022). "The raised circulating levels of CXCL8 we observe in tuberculosis patients correlate with previous reports." (PMID 16001981, 2005). "Increased levels of CCL2, CXCL8 and TNFα are reported in tuberculosis but their significance in different forms of tuberculosis is as yet unclear." (PMID 16001981, 2005). "Therefore, we predicted central DEGs in the PPI network and noted strong interactions between TNF, IL-6, IL-10, IL-1β, CSF-2, IL-4, CXCL8, IFN-γ, IL-1α, and CXCL1, all of which are strongly associated with tuberculosis." (PMID 37818041, 2023). "Furthermore, the expression of CCL20, CXCL8 and CXCL2 has been implicated in the pathogenesis of tuberculosis." (PMID 33057074, 2020). "We subsequently investigated LPS-induced CCL2, CXCL8 and TNFα in tuberculosis patients." (PMID 16001981, 2005). "IP-10/CXCL10 and IL-8/CXCL8 are involved in neutrophil and lymphocyte recruitment against M. tuberculosis (MTb) and disease progression of pulmonary tuberculosis (TB)." (PMID 24223729, 2013). "Studies on tuberculosis have demonstrated that IL-8 (CXCL8) is a chemokine produced mainly by macrophages and mesothelial cells, which plays a key role in the recruitment of lymphocytes and monocytes to the pleural space in TB patients." (PMID 34993156, 2021). "Interleukin 8 (CXCL8) is a chemoattractant and a regulator of white blood cell production, which can affect the pathogenesis of intense infectious diseases, such as TB, by suppressing the normal immune response to M. tuberculosis that can lead to granuloma formation." (PMID 31017900, 2019). "Circulating serum levels of CXCL8 and TNFα were raised in all tuberculosis patients, while CCL2 levels were not." (PMID 16001981, 2005). "Neither granulocytic accumulation, accumulation of IL1B or CXCL8 transcripts, nor M. tuberculosis labeling was detected in other TB samples investigated (n = 4)." (PMID 38385142, 2023). "Leucocyte activating chemokines such as CCL2, CCL3, and CXCL8 together with proinflammatory IFNγ, TNFα and downmodulatory IL10 play a central role in the restriction of M. tuberculosis infections, but is unclear whether these markers are indicative of tuberculosis disease severity." (PMID 20041183, 2009).
Allergy (49 papers, 2009 to 2025). An allergy is an immune response or reaction to substances that are usually not harmful. "Altogether, these findings show a persistent systemic inflammation in children with microcephaly due to CZS and suggest a possible impairment in leukocyte migration caused by low production of CCL2 and CXCL8, in addition to high levels of IgE associated with high prevalence of allergies." (PMID 37766239, 2023). "Moreover, IgE-binding monocytes have been described in horses and may be linked with allergy by triggering the release of CXCL8 supporting basophil recruitment." (PMID 39076967, 2024). "TNF-α and CXCL8 were reported to serve as important inflammatory cytokines by attracting neutrophils and basophils and promoting inflammatory reactions, not only in relation to allergies." (PMID 34299258, 2021). "Even in non-Th2 allergies, IL-17 induces airway epithelial cells to produce chemokines CXCL1 and CXCL8 to promote neutrophil recruitment while stimulating fibroblasts and macrophages to secrete cytokines such as GM-CSF, TNF, IL-1, IL-8, and IL-6 to enhance inflammatory responses." (PMID 35855823, 2022). "Basophils have pre-formed secretory granules containing pro-inflammatory cytokines, such as IL4, IL6, IL13, TSLP, GM-CSF and VEGF, and chemokines, such as CCL3, CCL4, CCL5 and CXCL8/IL8, in addition to histamine and granzyme B, and are widely known as a key player in allergy and parasitic infection." (PMID 36211375, 2022).
systemic inflammatory response syndrome (49 papers, 2011 to 2026). SIRS is a serious condition related to systemic inflammation, organ dysfunction, and organ failure. "Existing studies have demonstrated that CXCL8 can be used as a biomarker of systemic inflammatory response syndrome (SIRS); its up-regulation suggests short-term high mortality." (PMID 33968135, 2021). "Moreover, CXCL8 is also involved in pro-inflammatory signaling cascades along with other cytokines and plays a role in systemic inflammatory response syndrome (SIRS)." (PMID 36120307, 2022).
coronary artery disease (48 papers, 2008 to 2025). "In addition, elevated levels of IL-8/CXCL8 are associated with an increased risk of future coronary artery disease." (PMID 20107540, 2009). "In addition, activation of ICAM-1 also increased the expression of inflammatory genes correlated with coronary heart disease, such as IL-1B40, CXCL8, CCL541, and VCAM-143." (PMID 33758323, 2021). "Rothenbacher and colleagues demonstrated higher CXCL10 and CXCL8 and lower CCL5 levels in coronary heart disease patients compared with age- and gender-matched controls." (PMID 34835155, 2021).
osteosarcoma (48 papers, 2009 to 2026). A usually aggressive malignant bone-forming mesenchymal neoplasm, predominantly affecting adolescents and young adults. "A more recent study using preclinical models of osteosarcoma showed that pulmonary metastasis is initiated by a subpopulation of disseminated tumor cells that produce cytokines such as IL-6 and CXCL8 in response to lung-epithelium-derived IL-1α." (PMID 41008853, 2025). "Recently, it was found that NUCB2 enhanced osteosarcoma immune escape by elevating CXCL8 expression." (PMID 39309426, 2024). "In osteosarcoma, CXCL8 promotes migration and activates Akt signaling to promote survival in vitro, and CXCL8 inhibition or knock down (KD) of the receptor CXCR1 decreases lung metastases in vivo." (PMID 37025604, 2023). "According to the results of this study, and consistent with previous research, high levels of CXCL8/IL8 and IL6 are secreted primarily by cells of the TME and are associated with a poor survival prognosis for patients with osteosarcoma." (PMID 36354566, 2022). "Mesenchymal stem cell-derived CXCL8 promotes osteosarcoma cell anoikis resistance and pulmonary metastasis through CXCR1/Akt signaling." (PMID 35011369, 2021). "Large-scale purification of natural CXCL8 from diverse cellular sources including osteosarcoma cells (MG-63), fibroblasts, monocytes, endothelial and epithelial cells, revealed NH2-terminal sequence heterogeneity." (PMID 33777041, 2021). "CXCL8 derived from hBMMSCs was also shown to activate FAK signaling in osteosarcomas and to promote tumor metastasis." (PMID 33849537, 2021). "CXCL8 enhances tumor proliferation and metastasis through the interaction between human osteosarcoma and mesenchymal stem cells in the TME." (PMID 35011369, 2021). "To validate our nano-LC-MS/MS-based approach, we examined the presence of natural CXCL8 proteoforms in cell culture supernatant from osteosarcoma cells (MG-63) after partial purification by adsorption to CPG, heparin affinity and RP chromatography." (PMID 33777041, 2021). "Besides the STAT3-EMT and PI3K/AKT-FOXO1 signaling pathways, we found that new signals including CD44 and CXCL8 were also involved in DS−1-induced physiological regulation in human osteosarcoma U−2 OS cells." (PMID 35744840, 2022). "Osteosarcoma cell-derived CXCL8 was found to display NH2-terminal sequence heterogeneity." (PMID 33777041, 2021).
lymph node metastasis (47 papers, 2007 to 2025). "The current study revealed FN1, MMP9, and CXCL8 as potential biomarkers for identifying and predicting lymph node metastases." (PMID 37640804, 2023). "Multiple studies have shown that CXCL8 overexpression in ESCC patients is related to lymph node metastasis and worse prognosis." (PMID 33390169, 2021). "As for the presence of lymph node metastasis (N-factor), serum concentrations of CXCL-8 were higher in the N1 subgroup in comparison to patients without nodal involvement (N0 subgroup), but the differences were not significant." (PMID 32192002, 2020). "We found that CXCL8 protein was positively correlated with high tumor burden, including lymph node metastasis, advanced TNM stage, big tumor size, and poor OS time." (PMID 29636079, 2018). "We found that a high expression of CXCL8 was closely correlated with lymph node metastasis (p = 0.039), a high number of infiltrating CD204-positive macrophages (p = 0.043), and a high expression level of CXCR2 (p = 0.043)." (PMID 29285315, 2017). "In this work, lymph node metastasis in skin cutaneous melanoma was associated with CXCL2, in liver hepatocellular carcinoma with CXCL5, in kidney renal clear cell carcinoma with PPBP, and in esophageal carcinoma with CXCL8/IL-8." (PMID 37686093, 2023). "In conclusion, we believe that the expression of CXCL8 may be related to lymph node metastasis and distal metastasis in CRC patients, but its specific mechanism needs to be further studied." (PMID 35845924, 2022). "It suggested that the increase in CXCL8 might increase the frequency of lymph node metastasis." (PMID 36078096, 2022). "CXCL8 and its receptor CXCR2 (IL-8 Receptor, beta) are overexpressed in ESCC, and their level correlates with lymphatic invasion, venous invasion, lymph node metastasis, depth of invasion, and poor prognosis." (PMID 33390169, 2021). "Clinical data indicated that CXCL8 expression was significantly correlated with disease-free survival (DFS), lymph node metastasis, high expression levels of CXCR2, and high infiltration of an increased number of CD204-positive macrophages." (PMID 33390169, 2021). "We have previously demonstrated that serum CXCL8 levels significantly correlated with CRP levels and the presence of lymph node metastasis in PC patients." (PMID 32867211, 2020). "Notably, the preoperative PSA concentration, clinical tumor stage, and primary Gleason score were identified as significant predictors of lymph node metastasis, as were all evaluated CXC chemokine/receptors, with the exceptions of CXCR2 and CXCL8." (PMID 33195424, 2020). "Our previous study revealed that CXCL8 concentrations were significantly higher in patients with the presence of lymph node metastasis in comparison to patients without nodal involvement." (PMID 32867211, 2020). "Opposite results were obtained using the immunohistochemical method, where the authors demonstrated that the increased expression of both CXCL-8 and CXCR-2 correlated with the depth of invasion, lymph node metastasis, pathological stage, lymphatic and venous invasion." (PMID 30820705, 2019). "However, CXCL8 expression was higher in patients with lymph node metastasis than in the patients without lymph node metastasis." (PMID 36078096, 2022). "Moreover, ADC patients with lymph node metastasis expressed more CXCL8 than those without lymph node metastasis (p = 0.0065)." (PMID 29636079, 2018). "However, CXCL8 protein expression was not correlated with age (≤50 years compared with >50 years, P=0.527), tumor size (≤4 cm compared with >4 cm, P=0.812), and lymph node metastasis (absent compared with present; P=0.282)." (PMID 28883082, 2017).
oral squamous cell carcinoma (46 papers, 2007 to 2026). "Salivary and tissue CXCL8 is relevant in early diagnosis and prognosis of oral squamous cell carcinoma." (PMID 39199704, 2024). "For instance, CXCL1, CXCL2, CXCL8, and CCL5 are all related to the progression and diagnosis of oral squamous cell carcinoma." (PMID 39199704, 2024). "CXCL8 and PAI-1 secreted from oral squamous cell carcinoma promote the differentiation of monocytes to TAMs." (PMID 35011369, 2021). "Dysbiosis of the salivary microbiome contributes to the progression of oral squamous cell carcinoma (OSCC) by increasing inflammatory cytokines such as IL-6, CXCL8, TNF-α." (PMID 35011369, 2021). "Moreover, oral squamous cell carcinoma cell lines, including HSC2, respond to inflammatory cytokines IL1β and TNFα with an increased chemokine expression, including CXCL1, CXCL2, CXCL8, and CCL5." (PMID 39199704, 2024). "Moreover, oral squamous cell carcinoma cell lines, including HSC2, respond to inflammatory cytokines IL1β and TNFα with an increased expression of chemokines such as CXCL1, CXCL2, CXCL8, and CCL5." (PMID 39199704, 2024).
dry eye (44 papers, 2009 to 2024). "TUDCA supplementation also led to the transcriptional repression of CXCL8 and IL5, two inflammatory mediators associated with dry-eye pathogenesis." (PMID 35562919, 2022). "Patients with more severe dry eye have increased levels of IL-6 and IL-8/CXCL8 in their tears and similar increases are seen in the conjunctival epithelium in experimental dry eye models." (PMID 30002412, 2018). "We show that the alleviation of ER stress with the chemical chaperone TUDCA prevents cell death by reducing nuclear DNA fragmentation and caspase-3 activation, and represses the transcription of two inflammatory mediators, CXCL8 and IL5, that are associated with dry-eye pathogenesis." (PMID 35562919, 2022). "This is in agreement with previous studies in symptomatic, moderate dry eye patients, where there were no increases in levels of IL-1β, IL-6, IL-8/CXCL8, GRO-b, ICAM-1, TRAIL, or ephrin A5 in tear fluid." (PMID 20508732, 2010). "Since the increased expression of CXCL8 by resident tissues is an important mechanism for directing inflammation, it has been proposed that targeting IL8 could constitute a promising therapeutic approach for dry-eye patients." (PMID 35562919, 2022). "Interleukin-8 (IL-8), also called as chemokine (C-X-C motif) ligand 8 (CXCL8), a key cytokine that directs the migration of neutrophils, basophils and T-lymphocytes by mediating innate immune and angiogenic response, has consistently been reported to be elevated in tears of dry eye patients." (PMID 30673862, 2019).
heart failure (44 papers, 2012 to 2025). Inability of the heart to pump blood at an adequate rate to meet tissue metabolic requirements. "Concentrations of MCP-1/CCL-2, EOTAXIN/CCL11 and RANTES/CCL5 were significantly higher in the saliva of heart failure subjects with both NS and HS compared to the controls, while IL-8/CXCL8 level was considerably higher only in heart failure patients with NS." (PMID 36300113, 2022). "CXCL8 (IL-8) is a chemokine attracting neutrophils, which plays a key role in the early phase of reperfusion injury as well as in heart failure." (PMID 27242392, 2016). "It included proteins like NT-proBNP (NPPB), growth differentiation factor 15 (GDF15), and fibroblast growth factor 23 (FGF23), markers that are known to be tightly related to heart failure and further systemic diseases, but also inflammatory proteins (CXCL8, CSF1)." (PMID 38999939, 2024). "CXCL6 and CXCL8 belong to the cytokine family connected with heart failure and T2DM." (PMID 35663309, 2022). "Furthermore, primary cultured cardiac fibroblasts from severe heart failure patients exhibited LPS-induced cytokine production with increased expression of CCL2, IFNγ, IL1β, IL6, IL8/CXCL8, and TNFα." (PMID 33669239, 2021).
Cachexia (43 papers, 2009 to 2026). Severe weight loss, wasting of muscle, loss of appetite, and general debility related to a chronic disease. "A literature review highlights the significant role of pro-inflammatory cytokines, such as TNF-α, IL-6, and IL-1, and certain chemokines, like CXCL8/IL-8, as procachectic agents produced by different TME cell types in CRC-associated cachexia." (PMID 37629689, 2023). "TNF-α, IL-6, and IL-8/CXCL8 were identified as the most important factors in CRC induced cachexia involving CAAs." (PMID 33557173, 2021).
lung adenocarcinoma (43 papers, 2011 to 2025). A carcinoma that arises from the lung and is characterized by the presence of malignant glandular epithelial cells. "In turn, in lung adenocarcinoma cells, chronic hypoxia causes a change in the substrate specificity of dihydrodiol dehydrogenase which then starts to produce prostaglandin F2α (PGF2α), which increases the expression of CXCL8." (PMID 33467722, 2021). "High levels of CXCL8 (and CXCL1) in lung adenocarcinoma are linked to increased cancer risk and a poor disease prognosis, whereas low expression of CXCL1, CXCL7, and CXCL8 is associated with a better prognosis." (PMID 36164329, 2022). "Findings thus far suggested that overexpressed CXCL8 played a vital role in initiation and progression of lung adenocarcinoma (ADC) and presented early relapse and unfavorable prognosis of patients." (PMID 29636079, 2018). "Moreover, research on various clones of the A549 line (lung adenocarcinoma) demonstrates that CXCL8/IL-8 can impede tumor cell proliferation." (PMID 37686093, 2023). "On the other hand, there is a significant positive correlation between the expression of CDK1 and CXCL8 in patients with lung adenocarcinoma, suggesting that CDK1 may have a regulatory relationship with CXCL8." (PMID 36078096, 2022). "Through single cell analysis, we found that CXCL8 was mainly expressed in macrophages in lung adenocarcinoma samples, suggesting that CXCL8 may induce an immunosuppressive microenvironment through macrophages, thereby promoting tumor progression." (PMID 36078096, 2022). "In addition, the mRNA expression of IL-1 receptors, IL-1R1 and IL-1RAcp (Minna lab dataset, dbGaP Study Accession is phs001823.v1.p1), and response to IL-1β stimulation, which was measured as fold change in CXCL8 induction, were detected in immortalized normal cells and lung adenocarcinoma cells." (PMID 37985999, 2023). "In a KrasLAI-driven lung adenocarcinoma mouse model, CXCR2 ligand, C-X-C motif chemokine ligand 8 (CXCL8), is a transcriptional target of Ras and induces progression of premalignant lesion that is associated with infiltration of neutrophils." (PMID 34359674, 2021). "Chronic hypoxia does not alter CXCL8 expression in some cells, such as breast cancer cells, lung adenocarcinoma cells, primary hepatocytes and uveal melanoma cells." (PMID 33467722, 2021). "We also found the substantial expression of several chemokines (CXCL1, CXCL5, CXCL8, and CX3CL1) related to cell migration, invasion, metastasis, or EMT, in KRAS-mutant lung adenocarcinoma cell lines, which was also dependent on MAPK signaling (unpublished data)." (PMID 27846317, 2016).
Salmonella Infections (43 papers, 2007 to 2025). Infections with bacteria of the genus SALMONELLA. "After Salmonella infection, mRNAs encoding for CXCL8 (IL-8) were up-regulated in host cells infected by both WT and delta-hfq strains in LSMMG conditions." (PMID 38920683, 2024). "Moreover, CXCL8 was also enriched in many pathways, such as the NF-κB signaling pathway, the Toll-like receptor signaling pathway, salmonella infection, and influenza A infection." (PMID 34880865, 2021).